HCK (HCK proto-oncogene, Src family tyrosine kinase)
Description:
Non-receptor tyrosine-protein kinase found in hematopoietic cells that transmits signals from cell surface receptors and plays an important role in the regulation of innate immune responses, including neutrophil, monocyte, macrophage and mast cell functions, phagocytosis, cell survival and proliferation, cell adhesion and migration. Acts downstream of receptors that bind the Fc region of immunoglobulins, such as FCGR1A and FCGR2A, but also CSF3R, PLAUR, the receptors for IFNG, IL2, IL6 and IL8, and integrins, such as ITGB1 and ITGB2. During the phagocytic process, mediates mobilization of secretory lysosomes, degranulation, and activation of NADPH oxidase to bring about the respiratory burst. Plays a role in the release of inflammatory molecules. Promotes reorganization of the actin cytoskeleton and actin polymerization, formation of podosomes and cell protrusions. Inhibits TP73-mediated transcription activation and TP73-mediated apoptosis. Phosphorylates CBL in response to activation of immunoglobulin gamma Fc region receptors. Phosphorylates ADAM15, BCR, ELMO1, FCGR2A, GAB1, GAB2, RAPGEF1, STAT5B, TP73, VAV1 and WAS.
Synonyms: JTK9; AIPCV; p59Hck; p61Hck
Tractability: Small molecule: an approved drug acts on it; a structure with a bound ligand is known; a high-quality ligand is known; it has a high-quality binding pocket; it belongs to a druggable protein family. Antibody: UniProt places it where antibodies can reach, with high confidence; its Gene Ontology location is reachable by antibodies, with high confidence; the Human Protein Atlas places it where antibodies can reach. PROTAC: UniProt records ubiquitination sites on it; ubiquitination databases record sites on it; its protein half-life has been measured; a small molecule that binds it is known.
Target class: Kinase; TK protein kinase group; Enzyme; Protein Kinase; Tyrosine protein kinase Src family
Chemical probes: A 419259, DGY-06-116 (high quality)
Gene: Protein-coding gene on chromosome 20 (32,052,197 to 32,101,856, forward strand). Ensembl gene ENSG00000101336.
Subcellular location: Lysosome (Isoform 1); Membrane; Cell projection, podosome membrane; Cytoplasm, cytosol; Cell membrane (Isoform 2); Membrane, caveola; Cell junction, focal adhesion; Cytoplasm, cytoskeleton; Golgi apparatus; Cytoplasmic vesicle; Lysosome; Nucleus; Cytoplasmic vesicle, secretory vesicle
Subcellular location (Human Protein Atlas): Vesicles; Cytosol; Plasma membrane
Pathways (Reactome):
Immune System: FCGR activation; FLT3 signaling through SRC family kinases; Inactivation of CSF3 (G-CSF) signaling; Regulation of signaling by CBL; Signaling by CSF1 (M-CSF) in myeloid cells; Signaling by CSF3 (G-CSF)
Disease: FCGR3A-mediated IL10 synthesis; FCGR3A-mediated phagocytosis; Nef and signal transduction
Gene Ontology:
Molecular function: lipid binding; phosphotyrosine residue binding; protein binding; protein tyrosine kinase activity; non-membrane spanning protein tyrosine kinase activity; signaling receptor binding; ATP binding; protein kinase activity
Biological process: intracellular signal transduction; negative regulation of apoptotic process; peptidyl-tyrosine phosphorylation; positive regulation of cell population proliferation; protein autophosphorylation; regulation of actin cytoskeleton organization; regulation of cell shape; regulation of phagocytosis; regulation of podosome assembly; cell adhesion; cell differentiation; cell surface receptor protein tyrosine kinase signaling pathway; cytokine-mediated signaling pathway; Fc-gamma receptor signaling pathway involved in phagocytosis; innate immune response-activating signaling pathway; integrin-mediated signaling pathway; leukocyte degranulation; leukocyte migration involved in immune response; lipopolysaccharide-mediated signaling pathway; mesoderm development; negative regulation of inflammatory response to antigenic stimulus; positive regulation of actin filament polymerization; protein phosphorylation; regulation of inflammatory response; respiratory burst after phagocytosis; and 5 more
Cellular component: actin filament; caveola; cytoplasmic side of plasma membrane; cytosol; focal adhesion; lysosome; plasma membrane; cytoplasmic vesicle; cytoskeleton; Golgi apparatus; membrane; membrane raft; nucleus; transport vesicle
Genetic constraint (gnomAD): Loss-of-function variants: 37 observed, 61.22 expected, observed/expected ratio (o/e) 0.6, 90% interval 0.46 to 0.8. The upper end of that interval is the gene's LOEUF score, 0.8, which puts it in group 3 of 6, group 1 being the genes least tolerant of losing a copy. Missense variants: 549 observed, 682.81 expected, observed/expected ratio (o/e) 0.8, 90% interval 0.75 to 0.86. Synonymous variants: 239 observed, 256.33 expected, observed/expected ratio (o/e) 0.93, 90% interval 0.84 to 1.04.
Homologues: Orthologues: chimpanzee HCK (99% identical), macaque HCK (94% identical), dog HCK (91% identical), pig HCK (90% identical), rabbit HCK (88% identical), guinea pig HCK (87% identical), mouse Hck (86% identical), rat Hck (86% identical), zebrafish hck (72% identical), tropical clawed frog hck (61% identical). Paralogues in human: LYN (68% identical), LCK (63% identical), BLK (60% identical), YES1 (58% identical), FYN (58% identical), FGR (55% identical), SRC (55% identical), FRK (46% identical), ABL1 (39% identical), ABL2 (39% identical), SRMS (37% identical), PTK6 (36% identical), and 20 more.
Diseases named in the same sentence as HCK in open-access papers:
HCK is named in the same sentence as 114 diseases in open-access papers, as found by Europe PMC text mining. Sharing a sentence is not in itself a finding about the gene and the disease. The quoted sentences say what the papers report.
leukemia (16 papers, 2011 to 2025). A malignant (clonal) hematologic disorder, involving hematopoietic stem cells and characterized by the presence of primitive or atypical myeloid or lymphoid cells in the bone marrow and the blood. "Abnormal upregulation of HCK is associated with malignancies, including colorectal, gastric and breast cancers and various leukaemias, suggesting that HCK plays an important tumorigenic function." (PMID 34363435, 2021). "Excessive activation of HCK is associated with various leukemia, such as CML, multiple myeloma, and acute lymphoblastic leukemia, as well as solid malignancies including colorectal, breast, and gastric cancer." (PMID 32484210, 2020). "Excessive activation of HCK is reported to be associated with various leukemia, such as chronic myeloid leukemia (CML), multiple myeloma, and acute lymphoblastic leukemia, as well as solid malignancies including colorectal, breast, and gastric cancer." (PMID 32484210, 2020). "An oncogenic role of HCK has been implicated in human cancers, including leukemia and solid tumors of the breast, colon and stomach." (PMID 26087188, 2015). "Excessive HCK activation is associated with several types of leukemia and enhances cell proliferation and survival by physical association with oncogenic fusion proteins, and with functional interactions with receptor tyrosine kinases." (PMID 26087188, 2015). "High levels of HCK have been reported in various types of leukemia, such as multiple myeloma and acute lymphoblastic leukemia." (PMID 36183831, 2022). "Lineage-negative cells were transduced with the MLL-AF9 retrovirus from HCK+/+ and HCK−/− mice to generate an MLL-AF9-driven leukaemia model." (PMID 34167558, 2021). "As we observed that the self-renewal ability was dramatically reduced upon the third transplantation, we determined the LSC frequencies in the HCK+/+ and HCK−/− leukaemia cells of third recipient mice by a limiting dilution analysis." (PMID 34167558, 2021). "To better research the function of HCK in self-renewal, we performed RNA sequencing of leukaemia stem cells taken from the third recipient mice." (PMID 34167558, 2021). "The frequency of YFP+ leukaemia cells in the peripheral blood of the HCK−/− group was lower than that in the peripheral blood of the HCK+/+ group at 32 days after the second transplantation." (PMID 34167558, 2021). "We assessed the importance of HCK in leukaemogenesis by using a mixed-lineage leukaemia fusion protein (MLL-AF9)-driven mouse model of AML." (PMID 34167558, 2021). "Previous studies have shown that in leukemia breast and colon cancer the up-regulation of HCK protein is often accompanied by higher tumor grades and the prognosis of patients is mostly poor." (PMID 33186124, 2020). "HCK expression is elevated in various types of leukemia, and contributes to leukemogenesis through its association with the oncogenic fusion proteins BCR/ABL and TEL/ABL to enhance cell survival." (PMID 26087188, 2015). "It has been reported that HCK has oncogenic potential in Philadelphia chromosome-positive (Ph+) leukemia and lymphoma cells, however, other studies also demonstrated tumor suppressor functions for HCK in Ph− leukemias." (PMID 22248740, 2011). "The role of LCP1 and HCK in leukemia or lymphoma has been sporadically reported." (PMID 35771283, 2022). "The frequency of YFP+ leukaemia cells in the peripheral blood of the HCK−/− group was lower than that in peripheral blood of the HCK+/+ group at 32 days after the second transplantation, which was consistent with a decrease in the sizes and weights of the spleens of HCK−/− leukaemic recipient mice." (PMID 34167558, 2021). "Furthermore, the phenotypes resulting from HCK deficiency can be rescued by CDK6 overexpression, supporting that HCK maintains the self-renewal of leukaemia stem cells via CDK6 in AML." (PMID 34167558, 2021).
leukemia (continued). "HCK maintains the self-renewal of leukaemia stem cells via CDK6 in AML and may be an ideal therapeutic target for eradicating LSCs without influencing normal haematopoiesis." (PMID 34167558, 2021). "Next, we tested whether HCK inhibition was able to modulate CXCL12-induced chemotaxis of leukemia cells using a Transwell-based migration assay." (PMID 33842460, 2021). "In addition, we characterized the capacity of HCK amplification to lead to leukemia or MPN by reconstitution of mice with HSPCs overexpressing HCK." (PMID 31065022, 2019). "Moreover, HCK is required for leukemogenesis and leukaemia maintenance, indicating that HCK may be an ideal therapeutic target for small molecule anti-AML compounds." (PMID 34167558, 2021). "Moreover, HCK is required for leukemogenesis and leukaemia maintenance in vivo and in vitro." (PMID 34167558, 2021). "Moreover, HCK is required for leukaemogenesis and leukaemia maintenance in vivo and in vitro." (PMID 34167558, 2021). "Hematopoietic cell kinase (HCK) overactivation is related to LUAD and several types of leukemia." (PMID 35884544, 2022). "Inhibition of HCK reduces the PI3K-Akt, but also the MAPK signaling pathway, in cells with upregulated HCK expression and thereby HCK becomes a potential drug target in leukaemia." (PMID 33581643, 2021). "Functional roles of HCK in the self- renewal ability of LSCs, leukemogenesis and leukaemia maintenance have not previously been reported." (PMID 34167558, 2021). "As Src kinase family was described as a player in CXCL12/CXCR4 and PI3K or MAPK pathway in severe solid tumor, we hypothesized whether HCK could be a downstream target of CXCL12/CXCR4 pathway and contribute to the pathophysiology of leukemia cells." (PMID 33842460, 2021). "Although HCK is predominantly expressed in B lymphocyte progenitors, rather than in mature B lymphocyte, leukemias and many solid malignancies demonstrate a positive correlation between HCK activity and cancer cell proliferation and survival." (PMID 33233470, 2020). "Our in vivo reconstitution experiment however did not recreate the phenotype of leukemia as seen in those patients with del(20q) who were initially studied to identify evidence of HCK amplification." (PMID 31065022, 2019). "Leukemia was not noted even in mice reconstituted with PTPRT−/− HSPCs overexpressing HCK even after 12 month post primary transplantation and after secondary transplantation." (PMID 31065022, 2019). "All these confirmed the tumor-suppressive attributes of HCK in BCR-ABL negative leukemia." (PMID 38123749, 2025). "The frequency of YFP+ leukaemia cells in the peripheral blood of the tamoxifen-induced HCK−/− group was lower than that in the peripheral blood of the HCK+/+ group, which was consistent with a decrease in the sizes and weights of the spleens of HCK−/− leukaemic recipient mice." (PMID 34167558, 2021). "All mice reconstituted with PTPRT−/− HCK-over-expressing HSPCs revealed hyperphosphorylation of STAT3 but the precise copy numbers of HCK were not ascertained and it is possible that there is a gene dosage effect that is necessary to establish a MPN/leukemia phenotype." (PMID 31065022, 2019).
glioma (11 papers, 2020 to 2024). A benign or malignant brain and spinal cord tumor that arises from glial cells (astrocytes, oligodendrocytes, ependymal cells). "TOX expression was negatively associated with inflammatory activity signatures including HCK, LCK, MHC-I, MHC-II, STAT1, and interferon metagenes, but positively associated with the IgG metagene in pan-glioma analysis, LGG alone, and GBM alone." (PMID 32762688, 2020). "We then further investigated the effects of ALKBH5 expression on the tumor immune microenvironment (TIM) of glioma by screening seven metagenes, namely, HCK, IgG, Interferon, LCK, MHC-I, MHC-II, and STAT1, which reflect the status of inflammation and immune responses." (PMID 35444654, 2022). "Furthermore, based on seven clusters of metagenes, GSVA identified that ICOS was tightly associated with HCK, LCK, MHC-I, MHC-II, STAT1, and interferon, especially with LCK, suggesting a strong correlation between ICOS and T-cell activity in gliomas." (PMID 36276141, 2022). "The results showed that IgG, HCK, MHC-II, LCK, STAT1 interferon, B7-CD28, and TNF-related tumor immune responses were significantly enhanced with the increasing risk scores, indicating that the immune microenvironment in high-risk glioma patients regulates response changes." (PMID 37228500, 2023). "In both the TCGA and CGGA datasets, TREM1 expression was found to be positively correlated with HCK, interferon, LCK, MHC-I, MHC-II, and STAT1 metagenes but negatively correlated with IgG metagenes in glioma." (PMID 38370418, 2024). "Through high-throughput expression profiling, WGCNA, lasso, and multivariate Cox analysis, we acquired eight genes (HCK, HAVCR2, CD37, LPAR5, NAGA, C1QC, FCER1G and AIF1) to construct the MRGs signature in Grade II/III glioma patients." (PMID 33186124, 2020). "PDIA3 expression was positively correlated with HCK, LCK, MHC-I, MHC-II, STAT1, and interferon, but negatively related to IgG in pan-glioma and GBM analysis based on both TCGA and CGGA datasets." (PMID 32687065, 2020). "Consequently, TNFSF13 expression was identified positively correlated with interferon, STAT1, MHC-I, MHC-II, HCK, and LCK, while negatively relevant to IgG metagene in pan-glioma analysis and GBM alone analysis in both TCGA and CGGA databases." (PMID 34712225, 2021). "The relationship between B2M and seven inflammatory activity related signatures was then explored in pan-gliomas and LGG, B2M expression had positive correlation with HCK, LCK, MHC-I, MHC-II, STAT1 and interferon metagenes, and negative correlation with IgG metagene expression." (PMID 33658560, 2021). "We discovered that LIGHT expression exhibited a positive correlation with HCK, interferon, LCK, MHC-I, MHC-II, and STAT1 metagenes in all gliomas, while IgG exhibited a negative correlation with LIGHT expression based on the TCGA and CGGA datasets." (PMID 36341396, 2022).
breast carcinoma (8 papers, 2017 to 2026). "HCK has been reported to be highly expressed in breast cancer and its expression level is associated with the prognosis of breast cancer patients, which is considered to be a new biomarker and therapeutic target for breast cancer." (PMID 35185791, 2022). "Both tumor size (P=0.021) and HCK expression (P=0.005) were found to be independent predictors associated with DFS in breast cancer." (PMID 33162805, 2020). "In addition, the cBioPortal database showed the existence of mutation, amplification and fusion of HCK gene in breast cancer." (PMID 33162805, 2020). "It is interesting that quercetin was predicted to interact with PIM-1 and HCK proteins involved in breast cancer." (PMID 33946222, 2021). "Deregulated expression of HCK has been found in many solid tumors such as pancreatic, prostate, renal, and breast cancers 34-37." (PMID 33162805, 2020). "We further evaluated the level of HCK in serum of 40 breast cancer patients and 40 patients with benign breast disease by Elisa test." (PMID 33162805, 2020). "The database also showed that the level of HCK mRNA transcripts was higher in basal type breast cancer than that in HER2+ or luminal A/B type breast cancer." (PMID 33162805, 2020). "Analysis of the 87 breast cancer patients showed that HCK expression was related to a larger tumor size (P=0.008) and a greater number of PALNs (P=0.006), but not with other clinicopathological characteristics." (PMID 33162805, 2020). "The result presented that the ratio of HCK expression was significantly higher in metastatic tumors (like in chest wall, liver and lung) than that in primary breast cancer (P=0.028)." (PMID 33162805, 2020). "In different stage of breast cancer, patients with stage 4 had highest HCK mRNA expression and patients with stage 2 had lowest HCK mRNA expression." (PMID 33162805, 2020). "The level of HCK in serum was significantly higher in patients with breast cancer compared with patients with benign breast disease (P<0.01)." (PMID 33162805, 2020). "To obtain a more comprehensive conclusion, we conducted a meta-analysis of multiple datasets, and the results showed a significantly increased HCK mRNA expression in breast cancer tissues compared with normal tissues." (PMID 33162805, 2020). "Using the bioinformation databases, we preliminarily explored the HCK molecular function and regulation pathway to provide research directions to explore the mechanism by which HCK regulates the biological behaviors of breast cancer." (PMID 33162805, 2020). "In different gender of breast cancer patients, female patients had higher HCK mRNA expression than male patients (P<0.01)." (PMID 33162805, 2020). "In different molecular type of breast cancer, triple negative patients had higher HCK mRNA expression than HER2 positive and luminal type patients (P<0.01)." (PMID 33162805, 2020). "In different gender of breast cancer patients, male patients had higher level of HCK promoter methylation than female patients (P<0.01)." (PMID 33162805, 2020). "UALCAN dataset also gave us the chance to explore if promoter methylation of HCK was related to the clinicopathological characteristics of breast cancer patients, so as to promote the development of breast cancer." (PMID 33162805, 2020). "Next, our analysis of HCK expression in the prognosis of breast cancer showed that it was related to distant metastasis and death (P=0.002; P<0.001)." (PMID 33162805, 2020). "Studies that include more patients are therefore needed to explore the exact influence of HCK expression in breast cancer." (PMID 33162805, 2020). "In these 87 breast cancer patients, HCK expression was related to lower DFS and OS on Kaplan-Meier analysis." (PMID 33162805, 2020). "We assessed HCK expression and genetic variations in breast cancer using Oncomine, GEPIA, UALCAN, and cBioPortal databases." (PMID 33162805, 2020).